MPST (mercaptopyruvate sulfurtransferase)
Description:
Transfer of a sulfur ion to cyanide or to other thiol compounds. Also has weak rhodanese activity. Detoxifies cyanide and is required for thiosulfate biosynthesis. Acts as an antioxidant. In combination with cysteine aminotransferase (CAT), contributes to the catabolism of cysteine and is an important producer of hydrogen sulfide in the brain, retina and vascular endothelial cells. Hydrogen sulfide H(2)S is an important synaptic modulator, signaling molecule, smooth muscle contractor and neuroprotectant. Its production by the 3MST/CAT pathway is regulated by calcium ions.
Synonyms: MST; TST2; TUM1
Tractability: Small molecule: a structure with a bound ligand is known; it has a binding pocket of medium quality. PROTAC: ubiquitination databases record sites on it; its protein half-life has been measured.
Target class: Enzyme; Transferase
Gene: Protein-coding gene on chromosome 22 (37,019,635 to 37,029,822, forward strand). Ensembl gene ENSG00000128309.
Subcellular location: Cytoplasm; Mitochondrion; Synapse, synaptosome
Subcellular location (Human Protein Atlas): Mitochondria; Cytosol
Pathways (Reactome):
Metabolism: Degradation of cysteine and homocysteine
Gene Ontology:
Molecular function: protein binding; 3-mercaptopyruvate sulfurtransferase activity; sulfurtransferase activity; thiosulfate-cyanide sulfurtransferase activity; identical protein binding
Biological process: cyanate catabolic process; hydrogen sulfide biosynthetic process; response to toxic substance; sulfur amino acid catabolic process; tRNA wobble position uridine thiolation; kidney development; liver development; spinal cord development; transsulfuration
Cellular component: extracellular exosome; mitochondrion; cytoplasm; mitochondrial matrix; neuron projection; synapse
Genetic constraint (gnomAD): Loss-of-function variants: 24 observed, 22.47 expected, observed/expected ratio (o/e) 1.07, 90% interval 0.77 to 1.5. The upper end of that interval is the gene's LOEUF score, 1.5, which puts it in group 6 of 6, group 1 being the genes least tolerant of losing a copy. Missense variants: 470 observed, 398.22 expected, observed/expected ratio (o/e) 1.18, 90% interval 1.09 to 1.27. Synonymous variants: 196 observed, 170.94 expected, observed/expected ratio (o/e) 1.15, 90% interval 1.02 to 1.29.
Gene-disease validity (ClinGen):
ClinGen rates the evidence that MPST causes each of these diseases.
encephalopathy due to beta-mercaptolactate-cysteine disulfiduria (autosomal recessive): No Known Disease Relationship.
Homologues: Orthologues: chimpanzee MPST (99% identical), macaque MPST (92% identical), dog MPST (89% identical), pig MPST (82% identical), rat Mpst (79% identical), mouse Mpst (79% identical), guinea pig MPST (78% identical), tropical clawed frog mpst (62% identical), Caenorhabditis elegans mpst-7 (28% identical), Caenorhabditis elegans mpst-1 (26% identical), Caenorhabditis elegans mpst-3 (25% identical), Caenorhabditis elegans mpst-6 (25% identical), and 2 more. Paralogues in human: TST (56% identical).
Diseases named in the same sentence as MPST in open-access papers:
MPST is named in the same sentence as 58 diseases in open-access papers, as found by Europe PMC text mining. Sharing a sentence is not in itself a finding about the gene and the disease. The quoted sentences say what the papers report.
breast cancer (7 papers, 2021 to 2025). A primary or metastatic malignant neoplasm involving the breast. "As such, elevated levels for the MPST enzyme in our research may be considered as a positive potential response against breast cancer cells." (PMID 38397425, 2024). "However, the effect of pharmacological inhibition of endogenous H2S-producing enzymes (cystathionine-γ-lyase (CSE), cystathionine-β-synthase (CBS), and 3-mercaptopyruvate sulfurtransferase (3-MPST)) on the growth of breast cancer (BC) remains unknown." (PMID 35807290, 2022).
colon cancer (4 papers, 2020 to 2025). "Interestingly, MPST has been linked to the migration of murine colon cancer cell line CT26, raising the possibility of its involvement in the motility of cancer cells other than GB cells." (PMID 36310164, 2022). "High MPST activity and expression have been proven in numerous cancer cell lines and tissues, including human prostate tissue, urothelial carcinoma cells of bladder, colon cancer and human glioblastoma-astrocytoma and neuroblastoma cell lines." (PMID 32041330, 2020).
glioma (3 papers, 2014 to 2025). A benign or malignant brain and spinal cord tumor that arises from glial cells (astrocytes, oligodendrocytes, ependymal cells). "The expression levels of risk factors IL4I1, SMS, and ADI1 in high-grade gliomas were higher than those in lower‐grade gliomas, while the protein expression levels of protective factor GCLC, MSRB2, MTAP and MPST were exactly the opposite." (PMID 38057821, 2023). "The mean value of MPST, rhodanese and cystathionase activity, and sulfane sulfur level in human brain and gliomas." (PMID 25532835, 2014). "Because of the disappearance of γ-cystathionase activity in high-grade gliomas, it seems to be possible that 3-mercaptopyruvate sulfurtransferase could participate in hydrogen sulfide production." (PMID 25532835, 2014). "The investigations demonstrated that the level of sulfane sulfur in gliomas with the highest grades was high in comparison to various human brain regions, and was correlated with a decreased activity of γ-cystathionase, 3-mercaptopyruvate sulfurtransferase and rhodanese." (PMID 25532835, 2014).
ovarian carcinoma (3 papers, 2015 to 2023). A malignant neoplasm originating from the surface ovarian epithelium. "Expression changes and possible functional impact of ACTN1, MPST, ERP29 and SERPINB6 are reported for several cancers, but not for ovarian cancer." (PMID 29344361, 2018).
colitis (2 papers, 2023 to 2024). Inflammation of the colon. "We herein examined two types of model hapten-induced inflammation models, colitis (an inflammatory bowel disease model of mucosal immunity) and contact dermatitis (a type IV allergic model of systemic immunity), in CTH-deficient (Cth–/–) and MPST-deficient (Mpst–/–) mice." (PMID 36768979, 2023). "MPST−/− and MPST± mice exhibit exacerbated DSS-induced colitis." (PMID 39152482, 2024). "Treatment with a nonspecific CTH inhibitor propargylglycine exacerbated DSS-induced colitis in mice, and mRNA expression of three H2S-producing enzymes (CTH, MPST, and cystathionine β-synthase [CBS]) and H2S production was upregulated in the colon mucosa in the experimental colitis of mice/rats." (PMID 36768979, 2023).
Diabetes (2 papers, 2017 to 2025). "Our meta-analysis showed that PGRMC1, HADH, IRS1 and MPST were the four tissue non-specific genes presenting differential expression association with the diabetes or insulin response." (PMID 28117714, 2017). "Our analysis showed that PGRMC1 and HADH genes were significant over diabetes studies, while IRS1 and MPST genes were significant over insulin response studies, and joint analysis showed that HADH and MPST genes were significant over all combined data sets." (PMID 28117714, 2017).
Hypertension (2 papers, 2021). The presence of chronic increased pressure in the systemic arterial system. "Genetic deletion of 3-mercaptopyruvate sulfurtransferase (MST) is known to result in hypertension and cardiac hypertrophy in older mice, and is associated with increased anxiety-like behaviors." (PMID 33546491, 2021).
leukemia (2 papers, 2022 to 2024). A malignant (clonal) hematologic disorder, involving hematopoietic stem cells and characterized by the presence of primitive or atypical myeloid or lymphoid cells in the bone marrow and the blood. "The expression of MPST is altered in some leukemia cell lines, with enzyme expression potentially correlated with increased proliferative activity." (PMID 39062461, 2024). "This suggests that MPST may even play a role in the pathophysiology of certain types of leukemia." (PMID 39062461, 2024). "Various leukemia cell lines (REH, MV4-11, MOLM-14, and K562) have shown higher mRNA and protein levels of MPST, compared to cells from T-ALL leukemia." (PMID 39062461, 2024). "It seeks to identify potential bottlenecks in sulfur metabolism in leukemia cells, concentrating on four key enzymes: TST, MPST, CTH, and CBS." (PMID 39062461, 2024). "In different types of leukemia cell lines, such as REH, DND-41, MOLT-4, MV4-11, MOLM-14, and K562, gene expression for TST, MPST, CBS, and CTH was studied on the mRNA and protein level." (PMID 35204649, 2022). "In the present paper, we investigated the expression of TST, MPST, CTH, and CBS in the different types of human leukemia cell lines: B-ALL (REH cells), T-ALL (DND-41 and MOLT-4 cells), AML (MV4-11 and MOLM-14 cells), and CML (K562 cells)." (PMID 35204649, 2022). "In conclusion, our findings showed significant differences in the expression of TST, MPST, CTH, and CBS in different types of human leukemia cells." (PMID 35204649, 2022).
lung adenocarcinoma (2 papers, 2016 to 2022). A carcinoma that arises from the lung and is characterized by the presence of malignant glandular epithelial cells. "The protein levels of CBS, CSE and MPST were higher in lung adenocarcinoma tissues compared with adjacent normal lung tissues, accomplished by an increase in H2S biosynthesis." (PMID 36358533, 2022). "Similarly, lung adenocarcinoma cells, in comparison to normal lung epithelial cells, expressed higher levels of CBS, CSE and MPST and produced higher levels of H2S." (PMID 36358533, 2022). "Here we show that human lung adenocarcinoma tissue expresses high levels of hydrogen sulfide (H2S) producing enzymes, namely, cystathionine beta-synthase (CBS), cystathionine gamma lyase (CSE) and 3-mercaptopyruvate sulfurtransferase (3-MST), in comparison to adjacent lung tissue." (PMID 27808278, 2016).
melanoma (2 papers, 2023). A malignant, usually aggressive tumor composed of atypical, neoplastic melanocytes. "Interestingly, it was also found that in normoxia the expression and activity of 3-mercaptopyruvate sulfurtransferase in metastatic WM266-4 melanoma cells was significantly higher than in primary melanoma WM115 cells." (PMID 37892173, 2023). "Thus, it seems that MPST can play an important role in the progression of human melanoma cells (WM115 and WM266-4) compared to other sulfurtransferases such as TST and CTH, of which, expression in both cell lines was not changed." (PMID 37892173, 2023). "Therefore, it seems that modulating the expression/activity of MPST in metastatic melanoma cells by administering compounds that inhibit its activity may give promising results in further studies." (PMID 37892173, 2023). "Interestingly, it was found that in human metastatic WM266-4 melanoma cells the expression of MPST (on the mRNA and protein level) as well as the activity of MPST were significantly higher than in primary melanoma WM115 (both cell lines were developed from the same individual)." (PMID 37892173, 2023). "In this research paper, we examined the expression levels of sulfurtransferases (MPST, TST, CTH) and cystathionine beta-synthase in human primary (WM115) and metastatic (WM266-4) melanoma cell lines both in normoxic and hypoxic conditions." (PMID 37892173, 2023).
multiple sclerosis (2 papers, 2020 to 2022). A progressive autoimmune disorder affecting the central nervous system resulting in demyelination. "Multiple sclerosis is associated with decreased expression of the H2S-producing enzyme 3-mercaptopyruvate-sulfurtransferase, whereas H2S donor GYY4137 upregulates tolerogenic pathways." (PMID 35883859, 2022). "Furthermore, our in silico analysis of H2S-producing enzyme expression revealeda an elevated MPST expression in the Tregs of healthy donors, as well as the reduced MPST gene expression in the PBMCs from multiple sclerosis patients." (PMID 32664399, 2020).
osteoarthritis (2 papers, 2020 to 2024). A noninflammatory degenerative joint disease occurring chiefly in older persons, characterized by degeneration of the articular cartilage, hypertrophy of bone at the margins and changes in the synovial membrane. "TRPV2, a mechanosensitive Ca2+ channel, and MPST, a sulfurtransferase that generates the gasotransmitter H2S, are protective against cartilage degradation and calcification in in vivo models of surgically induced osteoarthritis." (PMID 38173036, 2024). "Several of these genes (MPST, TRPV2) were reported to protect against cartilage calcification in in vivo models of surgically induced osteoarthritis." (PMID 38173036, 2024).
pancreatic carcinomas (2 papers, 2020 to 2025). "Besides the altered expression of mCAT and cCAT in cancer, increased expression of MPST, the gene encoding for MST, was found in several types of cancer, including liver, colorectal, endometrial, stomach, prostate, urothelial, and pancreatic carcinomas." (PMID 32882966, 2020).
schizophrenia (2 papers, 2019 to 2025). A major psychotic disorder characterized by abnormalities in the perception or expression of reality. "None of the confounding factors, such as age at examination, BMI (body mass index), anti‐psychotic drug dose, age of onset of schizophrenia, duration of the illness, and smoking, were significantly correlated with MPST mRNA expression in scalp hair follicles." (PMID 31657521, 2019). "In this sample set, the MPST protein expression levels were higher in the schizophrenia than in the control groups." (PMID 31657521, 2019). "The expression levels of differentially expressed CBS and MPST were well correlated with each other in both the control and schizophrenia brain samples." (PMID 31657521, 2019). "In human brains, CAT was upregulated in schizophrenia samples compared to the controls (Fig EV5A), and the expression level of this gene was positively correlated with that of MPST and CBS in both the schizophrenia and control samples (Fig EV5B and C)." (PMID 31657521, 2019). "However, the MPST levels in PBCs exhibited no significant changes between subjects with schizophrenia and control, and plasma MPST protein levels were also unchanged between the two groups." (PMID 31657521, 2019). "In human postmortem brains [Brodmann area (BA) 8, frontal cortex] (1st sample set), RT–qPCR analyses revealed increased expressions of MPST and CBS in subjects with schizophrenia, with no change in CTH mRNA levels." (PMID 31657521, 2019).
acute lymphoblastic leukemia (1 paper, 2024). Leukemia with an acute onset, characterized by the presence of lymphoblasts in the bone marrow and the peripheral blood. "Similarly, MPST (p < 0.001, Log2FC = −1.098) and CBS (p < 0.001, Log2FC = −0.582) also exhibit higher expression levels in Acute Lymphoblastic Leukemia, whereas CTH expression is lower (p < 0.001, Log2FC = 0.644)." (PMID 39062461, 2024).
angiomyolipoma (1 paper, 2018). A neoplasm with perivascular epithelioid cell differentiation often associated with tuberous sclerosis. "Just to get an idea about basal expression of these enzymes in non-affected part of kidney, we compared expressions of CBS, CSE and MPST from a healthy part of kidney from patients with ccRCC and benign tumors (angiomyolipoma and oncocytoma)." (PMID 29793450, 2018). "Increase in MPST expression was observed in angiomyolipoma tumor of one patient and no change in MPST was detected in another angiomyolipoma." (PMID 29793450, 2018).
Cerebral ischemia (1 paper, 2024). Restriction of arterial blood supply to the brain associated with insufficient oxygenation to support the metabolic requirements of the tissue. "In addition, five proteins are shown to bind to neuroinflammation and cerebral ischemia, including parvalbumin alpha, superoxide dismutase, S‐adenosyl‐l‐homocysteine hydrolase, 3‐mercaptopyruvate sulfurtransferase, and cathepsin S." (PMID 38376040, 2024).
Chronic Myeloid Leukemia (1 paper, 2024). "Despite the absence of significant differences in mRNA and protein levels of MPST in Chronic Myeloid Leukemia K562 cells, a statistically significant difference was found in H2S levels compared to human CD34+ umbilical cord hematopoietic stem cells." (PMID 39062461, 2024). "Interestingly, Chronic Myeloid Leukemia (CML) exhibits the highest expression levels of MPST and CTH, along with very high TST expression." (PMID 39062461, 2024).
Down syndrome (1 paper, 2020). "The current study explored the possibility that a second H2S-producing enzyme, 3-mercaptopyruvate sulfurtransferase (3-MST), may also contribute to the development of functional deficits of Down syndrome cells." (PMID 32340322, 2020).
endometrial carcinoma (1 paper, 2025). A malignant tumor arising from the epithelium that lines the cavity of the uterine body. "We conducted an investigation of the SLC2A1 and MPST genes using 549 Uterine Corpus Endometrial Carcinoma (UCEC) samples with mutations." (PMID 40746529, 2025). "In this study, we have firmly established the diagnostic and prognostic significance of SLC2A1 and MPST in Uterine Corpus Endometrial Carcinoma (UCEC)." (PMID 40746529, 2025). "Following the database analysis, we used quantitative Polymerase Chain Reaction (qPCR) to measure the expression levels of SLC2A1 and MPST in tissue samples from patients with Uterine Corpus Endometrial Carcinoma (UCEC)." (PMID 40746529, 2025). "To better understand the significance and mechanisms of SLC2A1 and MPST expression in Uterine Corpus Endometrial Carcinoma (UCEC), we investigated the relationship between the expression levels of these proteins and various clinical features." (PMID 40746529, 2025). "Both SLC2A1 and MPST showed high expression in endometrial cancer clinical samples and in the TCGA database." (PMID 40746529, 2025).
endotoxemia (1 paper, 2018). "In LPS-treated mice the findings of indicated that a deficiency in MPST does not significantly affect endotoxemia but a deficiency in CBS or CSE slightly ameliorates the outcome of LPS-induced endotoxemia in vivo." (PMID 30386265, 2018).
fatty liver disease (1 paper, 2022). A reversible condition wherein large vacuoles of triglyceride fat accumulate in liver cells via the process of steatosis. "Of the 15 identifed proteins, MPST was reported to be a potential therapeutic target for NAFLD, and that the fatty acids promote fatty liver disease via the dysregulation of the MPST/hydrogen sulfide pathway (Ref." (PMID 35741222, 2022).
ischemia (1 paper, 2016). A hypoperfusion of the BLOOD through an organ or tissue caused by a PATHOLOGIC CONSTRICTION or obstruction of its BLOOD VESSELS, or an absence of BLOOD CIRCULATION. "Meanwhile, in ischemia myocardium, three H2S-producing enzymes, cystathionine γ-lyase (CSE), cystathionine-β-synthase (CBS), and 3-mercaptopyruvate sulfurtransferase (3-MST) significantly increased." (PMID 27057284, 2016).
renal carcinoma (1 paper, 2018). A carcinoma arising from the epithelium of the renal parenchyma or the renal pelvis. "In the functional importance of our observation we proposed that CBS, CSE and/or MPST expression in renal cancer might be associated with the apoptosis induction." (PMID 29793450, 2018). "Therefore, the main goal of this work was to evaluate expression of CBS, CSE and MPST in patients diagnosed with renal cancer and try to associate results with apoptosis induction in vitro." (PMID 29793450, 2018). "Particularly, we determined the expression and localization of CSE, CBS and MPST in renal carcinomas of 26 patients compared to matching unaffected part of kidney." (PMID 29793450, 2018).